ENSG00000252083
Synonyms: LOC124900210
Gene: Small nucleolar RNA gene on chromosome 5 (23,972,188 to 23,972,294, reverse strand). Ensembl gene ENSG00000252083.
Gene Ontology:
Biological process: RNA processing
Cellular component: nucleolus
Homologues: Paralogues in human: SNORA40B (91% identical), SNORA40 (89% identical), SNORA40C (86% identical).